PXN (paxillin)
Diseases named in the same sentence as PXN in open-access papers (continued):
Sharing a sentence is not in itself a finding about the gene and the disease.
neuroblastoma (10 papers, 2013 to 2025). Neuroblastoma (NB) is the most common solid, extracranial childhood tumor. "Src, FAK, and paxillin proteins are expressed in human neuroblastoma cell lines, SK-N-AS and SK-N-BE, and children with concomitant positivity tumors have poor survival." (PMID 38201459, 2023). "The FAK-Src-paxillin system is recognized as a marker of poor prognosis in human neuroblastoma patients." (PMID 37175948, 2023). "Combined and concurrent inhibition of the FAK-Src-Paxillin system has been proposed as a therapy to inhibit neuroblastoma tumor growth and metastases." (PMID 27009842, 2016). "The Src-FAK-Paxillin pathway is responsible for poor prognosis in neuroblastoma patients." (PMID 38201459, 2023). "On the other hand, the FAK-Src-paxillin protein system, consisting of FAK, Src, and paxillin proteins, is associated with an aggressive phenotype in adult malignancies and increases mortality in children with neuroblastoma." (PMID 37175948, 2023). "In addition, a recent study demonstrated that VPA induces the neurite outgrowth of mouse neuroblastoma N1E-115 cells through a JNK-paxillin unit." (PMID 28321599, 2017). "For example, concomitant FAK, Src and paxillin tumour positivity and myelocytomatosis oncogene (MYCN) amplification had statistically significant increased mortality in children with neuroblastoma." (PMID 39036223, 2024). "We showed that paxillin phosphorylation, acting through the Rac1/Cdc42/cJNK signaling cascade, is activated following neurite extension in mouse N1E115 neuroblastoma cells." (PMID 23626709, 2013). "Thus, the JNK phosphorylation of paxillin, possibly after Rac1/Cdc42 signaling cascade stimulation, plays a critical role in neurite extension in mouse N1E115 neuroblastoma cells." (PMID 23626709, 2013).
ovarian carcinoma (9 papers, 2012 to 2024). A malignant neoplasm originating from the surface ovarian epithelium. "In this study, we evaluated the PXN expression in ovarian cancer and its association with patient prognosis." (PMID 36923874, 2023). "Then, enrichment analyses were conducted to explore the underlying mechanism of PXN in ovarian cancer." (PMID 36923874, 2023). "Further, we explored the possible underlying mechanism of PXN in ovarian cancer." (PMID 36923874, 2023). "Moreover, highly expressed PXN was linked to poor PPS in ovarian cancer (P < 0.05) and poor PFS (P < 0.001) in liver cancer." (PMID 34135128, 2021). "By comprehensive use of various bioinformatics tools, we analyzed the expression of PXN and its prognostic value in ovarian cancer." (PMID 36923874, 2023). "Although PXN proved to be valuable in determining prognosis and guiding treatment in ovarian cancer patients, it should be prospectively confirmed by large-sample clinical studies." (PMID 36923874, 2023). "Significant negative relationships between PXN expression and immune infiltrates were observed, however, PXN was positively connected with immune checkpoint (VSIR) in ovarian cancer." (PMID 36923874, 2023). "For strengths, our study comprehensively investigates the PXN expression and prognosis in ovarian cancer." (PMID 36923874, 2023). "Due to the essential role of the tumor immune microenvironment in ovarian cancer, we assessed the correlation of PXN expression with infiltration levels of six tumor immune cells using the TCGA data." (PMID 36923874, 2023). "IHC analysis showed that higher protein level of PXN in ovarian cancer tissue than normal ovary tissue." (PMID 36923874, 2023). "Then, the enrichment analyses were conducted to determine the possible regulatory pathways PXN involved in ovarian cancer." (PMID 36923874, 2023). "To elucidate the pathological role of PXN in ovarian cancer, we performed a functional enrichment analysis of PXN and its co-expressed genes." (PMID 36923874, 2023). "Upregulated PXN expression was linked to poor prognosis and OS in many cancers, including GBM, HNSC, acute myeloid leukemia, LGG, LIHC, LUSC, mesothelioma (MESO), ovarian cancer, pancreatic adenocarcinoma (PAAD), and skin cutaneous melanoma (SKCM)." (PMID 34135128, 2021). "However, there is a lack of systemic research on the expression and the prognostic role of PXN in ovarian cancer." (PMID 36923874, 2023). "Our study demonstrated the potential function of PXN in ovarian cancer." (PMID 36923874, 2023). "PXN serves as a reliable prognostic biomarker and may be a potent therapeutic target for ovarian cancer." (PMID 36923874, 2023). "PXN was highly expressed in ovarian cancer and its expression could independently predict the overall survival of ovarian cancer patients." (PMID 36923874, 2023). "In conclusion, PXN is highly expressed in ovarian cancer compared with normal tissues." (PMID 36923874, 2023). "Consistently, PXN remained an independent prognostic factor for patients with ovarian cancer." (PMID 36923874, 2023). "Besides, PXN can independently predict the OS of ovarian cancer patients and exhibit relatively satisfactory performance in predicting long-term survival." (PMID 36923874, 2023). "It has been demonstrated that upregulated VSIR on the tumor-infiltrating myeloid cells promotes tumor growth via suppressing T cell immunity, indicating that PXN might exhibit certain functions in immunotherapy for ovarian cancer." (PMID 36923874, 2023). "In addition, earlier experiments from our group have shown that the activation of PAFR has pleiotropic effects on tyrosine phospho-EGFR/Src/Paxillin in ovarian cancer." (PMID 24886678, 2014). "However, both colorectal and ovarian cancers presented an entirely different clinical association of these genes with only one gene in each cancer type (colorectal: B3GNT1, ovarian: PXN) associated with poor prognosis." (PMID 25587357, 2014).
ovarian carcinoma (continued). "Therefore, the authors speculated that PXN might affect the poor prognosis of ovarian cancer patients through activation of these pathways and accelerating cancer metastasis." (PMID 36923874, 2023). "Moreover, high PXN expression may affect ovarian cancer progression via positive regulation of metastasis-related pathways." (PMID 36923874, 2023). "Using the TCGA-ovarian cancer and GSE63885 datasets, we drew Kaplan-Meier plotter curves and observed that patients with high PXN expression had worse clinical outcomes." (PMID 36923874, 2023). "High PXN expression levels were observed in UVM (66.7%), thyroid carcinoma (54%), testicular germ cell tumors (41.7%), GBM (27.3%), HNSC (25%), ovarian cancer (25%), PRAD (18.2%), DLBC (16.7%), SKCM (16.7%), COAD (10%), BLCA (9.1%), and BRCA (9.1%)." (PMID 34135128, 2021). "Local anesthetic lidocaine suppresses the metastasis of ovarian cancer and sensitizes cisplatin through blocking NaV1.5‐mediated EMT and FAK/paxillin signaling pathway." (PMID 33280262, 2021). "We found that mesenchymal-like chemoresistant IGROV1 ovarian cancer cells have higher migration properties because of their rapid regulation of focal adhesion dynamics through FAK, paxillin, vinculin, and talin." (PMID 32079527, 2020). "Another study in the context of ovarian cancer reported that a VGSC-targeting drug, lidocaine, hinders the metastatic capabilities of ovarian cancer by impeding Nav1.5-mediated EMT and the focal adhesion kinase/Paxillin signaling pathway." (PMID 39060933, 2024). "Through expression analysis, we found that PXN was highly expressed in ovarian cancer, but its expression was not significantly related to age, grade, tumor residual disease, and stage." (PMID 36923874, 2023). "Our data may indicate that lidocaine suppresses the metastasis of ovarian cancer and sensitizes cisplatin through blocking NaV1.5‐mediated EMT and FAK/paxillin signaling pathway." (PMID 33280262, 2021).
bladder cancer (7 papers, 2009 to 2024). "KiSS-1 has also been shown to influence cell adhesion by forming focal adhesions through phosphorylation of focal adhesion kinase and paxillin, and an association between loss of KiSS-1 expression and E-cadherin expression was reported in bladder cancer." (PMID 19154616, 2009). "In addition, discrete groups of tumor cells were found to be associated with oncostatin M signaling, bladder cancer signaling, and paxillin signaling." (PMID 28977854, 2017). "The targeting of FAK/paxillin pathways with some small-molecule drugs has been evaluated in bladder cancer studies with promising preliminary results." (PMID 33240083, 2020). "Another mechanism regarding the actions of PGRN covers the formation of protein tyrosine kinase 2 (PTK2) and paxillin (PXN) complex through ERK1/2 activation that promotes cell invasion and migration, as observed in bladder cancer and mesothelioma." (PMID 38247816, 2024). "In bladder cancer, progranulin promotes cell migration and invasion by inducing the formation of a molecular complex containing focal adhesion kinase (FAK) and paxillin, in an ERK1/2-dependent manner." (PMID 36980592, 2023). "In bladder cancer, antrocin inhibits migration and invasion by suppressing the ERK/FAK/paxillin and ERK/c-Fos/MMP-2 signaling pathways." (PMID 30602706, 2018). "Furthermore, in bladder cancer, progranulin-dependent activation of MAPK favors the formation of a complex containing paxillin and FAK, thereby promoting cell migration and invasion." (PMID 36980592, 2023).
breast tumor (7 papers, 2008 to 2023). "Several studies have reported that paxillin overexpression is associated with alterations and malignant progression of breast tumors." (PMID 33614634, 2020). "The downregulation of paxillin resulted in a reduced invasion of primary breast tumors and made tumor organoids less invasive in 3D collagen cultures, whereas the overexpression of paxillin made cancer cells more aggressive." (PMID 37175948, 2023). "The phosphorylation of paxillin by kinases such as the Src family enables breast tumor cells and metastatic breast tumor cells with a basal-like phenotype to exhibit enhanced invasiveness in confined spaces." (PMID 37175948, 2023). "Our findings have shown that as a result of the combined stimulation by TNFα + Estrogen + EGF, luminal breast tumor cells have gained an extensive spreading phenotype in which Src activation has given rise to tumor cell spreading and to localization of FAK and paxillin in tumor cell protrusions." (PMID 24369447, 2013).
lung adenocarcinoma (7 papers, 2015 to 2025). A carcinoma that arises from the lung and is characterized by the presence of malignant glandular epithelial cells. "The patients with lung adenocarcinoma in the TCGA database who had high PXN expression showed poorer outcomes and shorter overall survival (p = 0.004)." (PMID 40634277, 2025). "C-Met, β1-integrin, and paxillin were identified as novel components of TNTs in A549 lung adenocarcinoma cells." (PMID 37550007, 2023). "This study identifies c-Met, β1-integrin, and paxillin as novel components of TNTs in A549 lung adenocarcinoma cells, with paxillin localised at the protrusion site of TNTs." (PMID 37550007, 2023). "MiR-218-5p and miR-24-3p have also been reported to suppress the NK killing effect in CRC by targeting paxillin (PXN) and in lung adenocarcinoma by targeting Serine Hydroxymethyltransferase 1 (SHMT1), respectively." (PMID 36189271, 2022). "In A549 lung adenocarcinoma cells, it has been shown that silencing of CD151 has major effects on downstream tyrosine phosphorylation signaling events involving p130Cas, FAK, paxillin and Src." (PMID 25814554, 2015).
lymph node metastasis (7 papers, 2012 to 2023). "For example, paxillin overexpression is associated with tumor aggressiveness, poor tumor differentiation, and lymph node metastasis in LSCC, and paxillin is a predictor of poor survival and recurrence-free survival." (PMID 37175948, 2023). "The expression of paxillin has also been observed as closely associated with the prognosis and the lymph node metastasis of NSCLC patients." (PMID 32457792, 2020). "The expression of both TNC and Paxillin were increased in tissues of squamous cell carcinoma with lymph node metastasis." (PMID 29088796, 2017). "The expression levels of SEPT9 and paxillin were significantly increased in the lymph node metastasis group compared to the non-lymph node metastasis group, and SEPT9 expression was positively correlated with lymph node metastasis (γ = 0.367, P = 0.006)." (PMID 31558699, 2019). "Paxillin expression was negatively correlated with tumor size, depth of invasion, and lymph node metastasis, but not with gender, lymphatic or venous invasion, or TNM staging (P>0.05)." (PMID 24348846, 2014). "Paxillin expression was negatively correlated with tumor size, depth of invasion and lymph node metastasis, but not with patient gender, lymphatic or venous invasion, or TNM staging (P>0.05)." (PMID 24348846, 2014). "The high expression of fascin-1, ezrin or paxillin was positively correlated with poor tumor differentiation, cervical lymph node metastasis (N+), and advanced clinical stage (III+IV) (P<0.05) but not sex or metastasis." (PMID 23209815, 2012).
liver cancer (6 papers, 2021 to 2024). An epithelial or non-epithelial malignant neoplasm that arises from the liver. "Similar to the current study, also demonstrated involvement of paxillin signaling in PFAS dependent changes in liver cancer cells." (PMID 38535903, 2024). "Microcystin-LR (MC-LR) promotes the adhesion ability of liver cancer cells by activating the MAPK/ERK1/2 signaling pathway to phosphorylate paxillin." (PMID 37175948, 2023). "In order to explore the molecular mechanism by which ITGAV promotes tumorigenesis of liver cancer, the protein expression of BCL2, PXN, and MAPK was detected after overexpression and knockdown of ITGAV." (PMID 38374893, 2024). "The overexpression of HAb18G/CD147 has been proven to promote the migration of liver cancer cells by increasing the expression of integrin α3β1 and activating the integrin-FAK signaling pathway to increase the expression of paxillin." (PMID 37175948, 2023). "It is suggested that ITGAV may play important roles in tumorigenesis of liver cancer by activating the expression of BCL2, PXN, and MAPK." (PMID 38374893, 2024). "This indicated that ITGAV may play important roles in tumorigenesis of liver cancer by activating the expression of BCL2, PXN and MAPK." (PMID 38374893, 2024).
triple-negative breast carcinoma (6 papers, 2017 to 2023). An invasive breast carcinoma which is negative for expression of estrogen receptor (ER), progesterone receptor (PR), and human epidermal growth factor receptor 2 (HER2). "At the same time, lncRNA DLX1-AS231, miR-199b-5p, and paxillin can also form a ceRNA network to regulate the proliferation, EMT, and cisplatin resistance of triple-negative breast cancer cells." (PMID 37175948, 2023). "Hesperetin can inhibit triple-negative breast cancer cell migration and invasion by inhibiting the TGF-β1-mediated Fyn/paxillin/RhoA signaling pathway." (PMID 37175948, 2023). "Mixed-lineage kinase 3 (MLK3), a mitogen-activated protein kinase kinase kinase (MAP3K), has critical roles in metastasis of triple-negative breast cancer (TNBC), in part by regulating paxillin phosphorylation and focal adhesion turnover." (PMID 28604765, 2017). "In triple-negative breast cancer, the lncRNA DLX6 antisense RNA 1 was upregulated in cancer tissues, and its expression promoted cell proliferation, EMT, and cisplatin resistance by regulating the miR-199b-5p/PXN axis." (PMID 34946859, 2021).
esophageal cancer (5 papers, 2014 to 2023). A primary or metastatic malignant neoplasm involving the esophagus. "A novel indole compound, SK228, was shown to disrupt the F-actin cytoskeleton and FAK/paxillin signaling axis in the sub-micromolar range to inhibit the growth of different lung and esophageal cancer cell lines." (PMID 37175948, 2023). "We found that PXN expression was upregulated in human tumors (cholangiocarcinoma, esophageal carcinoma, GBM, HNSC, LIHC, thyroid carcinoma, PRAD, stomach adenocarcinoma, and kidney chromophobe) compared with corresponding normal tissues." (PMID 34135128, 2021). "Furthermore, the inhibition of paxillin phosphorylation inhibits esophageal cancer cell migration by inhibiting Rac1 prenylation and reducing its activation." (PMID 37175948, 2023). "As a local anesthetic, ropivacaine can reduce the activity of small GTPase by inhibiting the prenylation of small GTPase, which can inhibit the phosphorylation level of paxillin by inhibiting the MAPK/JNK signaling pathway, thereby reducing the migration of esophageal cancer cells." (PMID 37175948, 2023).
head and neck squamous cell carcinoma (5 papers, 2021 to 2025). A squamous cell carcinoma that arises from any of the following anatomic sites: lip and oral cavity, nasal cavity, paranasal sinuses, pharynx, larynx, and salivary glands. "In a study of head and neck squamous cell carcinoma, integrin can regulate the activity of paxillin and downstream Rac1 through the FAK/Src complex to complete the cell migration process." (PMID 38791597, 2024). "In the head and neck squamous cell carcinoma (HNSCC) cell models, the downregulation of paxillin contributes to the attenuation of tumor cell invasion and metastasis." (PMID 40821990, 2025).
oral squamous cell carcinoma (4 papers, 2022 to 2024). "Shekhar and Angadi studied the pattern of PXN expression in varying grades of carcinoma and concluded that the PXN might be involved in the progression and growth of oral squamous cell carcinoma." (PMID 38962075, 2024). "However, the roles of paxillin in epithelial dysplasia (ED), oral squamous cell carcinoma (OSCC), oral lichen planus with dysplasia (OLPD), hyperkeratosis (HK), and oral lichen planus (OLP) have remained unnoticed in the literature." (PMID 37568839, 2023). "PIX-GIT1 also modulates focal adhesion formation, invasion, and metastasis of oral squamous cell carcinoma via regulation of FAK, paxillin, ERK1/2, and MMP2/935." (PMID 35318302, 2022).
renal cell carcinoma (4 papers, 2021 to 2024). "Immunohistochemical analysis in our study showed that FAK, Src and paxillin proteins are expressed in a portion of the renal cell carcinoma cases." (PMID 39036223, 2024). "Elevation of many integrin molecules may trigger metastasis in renal cell carcinoma, moreover, integrins also activate Akt via FAK, paxillin, and integrin-linked kinase." (PMID 38680858, 2024).
tongue squamous cell carcinoma (4 papers, 2021 to 2023). A squamous cell carcinoma that arises from the tongue. "The high expression of p-paxillin in mobile tongue squamous cell carcinoma is associated with higher tumor invasiveness, metastasis, poorer disease-free survival, and overall survival time." (PMID 37175948, 2023). "Moreover, carbon ion treatment, in combination with FAK silencing, markedly blocked the phosphorylation levels of FAK, and paxillin, which partly contributed to the reduced motility of tongue squamous cell carcinoma CAL27 cells." (PMID 33634070, 2021). "Moreover, phosphorylated paxillin is closely related to poor prognosis of patients with mobile tongue squamous cell carcinoma." (PMID 34268882, 2021).
esophageal squamous cell carcinoma (3 papers, 2015 to 2023). Esophageal squamous cell carcinoma (ESCC) is a type of esophageal carcinoma (EC) that can affect any part of the esophagus, but is usually located in the upper or middle third. "As a transcriptional repressor, the CCCTC-binding factor (CTCF) can regulate the transcriptional inactivation of miR-137 to promote the expression of paxillin to promote EMT and radioresistance in esophageal squamous cell carcinoma." (PMID 37175948, 2023). "In esophageal cancers, SLIT2 is a migration suppressor for ESCC (esophageal squamous cell carcinoma) via inhibition of srGAP–Cdc42 signaling and membrane localization of p-FAK and p-Paxillin." (PMID 26674478, 2015).